KRAS (KRas proto-oncogene, GTPase)
Diseases named in the same sentence as KRAS in open-access papers (continued):
Sharing a sentence is not in itself a finding about the gene and the disease.
tumor (continued). "These different subtypes classify tumours with distinguishing features such as microsatellite instability (MSI), high/hypermutated/BRAF mutated (CMS1), WNT activated (CMS2), metabolic/KRAS mutated (CMS3) and EMT/TGF-β activated (CMS4)." (PMID 33879799, 2021). "As another limitation, we did not have the necessary data to assess the association of E. coli and ETBF sero-positivity with CRC by molecular status of the tumor (e.g., MSI or APC and KRAS mutation status)." (PMID 33874856, 2021). "In 14/15 (93.33%) patients with later on determined tumor tissue KRAS mutational status, the SNV detected by ddPCR in plasma (cfKRASmut) at any time point matched the KRAS SNV detected in tissue analysis, confirming the validity of ddPCR cfKRASmut analysis." (PMID 33430810, 2021). "Expression was next evaluated in tumours harbouring multiple mutations, where ALOX5 expression was significantly reduced in tumours with a KRAS and LKB1 mutation." (PMID 34203378, 2021). "Treatment of mice bearing sizable (~200 mm3) subcutaneous KRAS G12D tumors with ISRIB resulted in a substantial suppression of tumor growth." (PMID 34330898, 2021). "Eight mice, harbouring orthotopic tumours of the 3LL ΔNRAS cell line, were treated for 7 days with the KRAS G12C inhibitor MRTX1257 (n = 3) or vehicle (n = 5)." (PMID 34625563, 2021). "One patient was reported carrying 12p gain on both GCNIS and in primary TGCT, while KRAS mutation was detected only in the TGCT, suggesting the two alterations are separate processes acquired during tumor evolution." (PMID 34680371, 2021). "We identified that up to 9.1% of the isolated CHCs harbored an oncogenic KRAS allele while the leukocyte fraction only expressed wild type KRAS, indicating that CHCs derive from the primary tumor and retain key genomic drivers of cancer progression." (PMID 34211050, 2021). "Regarding survival in patients with KRAS wt and KRAS mut tumours, our results are consistent with other studies." (PMID 34503114, 2021). "We found that in CT26 (KRAS-G12D) mouse model, the combined treatment of oHSV T3855 with MEKi showed 100% complete tumor eradication while LLC (KRAS-G12C) showed 50% complete response at 4 weeks post treatment." (PMID 34578339, 2021). "A recent study showed that hyperactivation of p-ERK by the pharmacological inhibition of DUSPs can exert anti-proliferative and anti-tumor effects in mutant KRAS LUAD cells." (PMID 34330898, 2021). "Using limiting dilution assays in nude mice, we estimated that the frequency of tumor-initiating cells (TIC) ranged from 0.7% in KRAS intact KC/KPC cells to ~0.35% in KRAS KO cells." (PMID 33674596, 2021). "We show for the first time that melatonin attenuates PD-L1 expression through suppressing YAP/TAZ and thereby modulating tumor immunity in KRAS-mutant NSCLC." (PMID 34073318, 2021). "BRAF alterations have been shown to be mutually exclusive with KRAS mutations, and represent another potential therapeutic target in KRAS wild-type tumours." (PMID 34956889, 2021). "On the contrary, TP53TG1 promotes tumor growth by binding to miR-96 to enhance KRAS activation in PDAC." (PMID 34564314, 2021). "Across all tumour types, in a large PanCancer analysis, KRAS was the most diverse oncogene, being labelled as a driver mutation in 16 different primary sites." (PMID 34200676, 2021). "An analysis of EC patients from the Tumor Cancer Genome Atlas (TCGA) showed that KRAS mutant ECs have increased activation of estrogen signaling, by means of increased RAS/MAPK pathway signaling." (PMID 34064352, 2021). "Mutated KRAS induces ERK activation and tumor progression by activating the formation of RAF homo- or heterodimers." (PMID 33917906, 2021). "Here, we show that combined treatment with fibroblast growth factor receptor 1 (FGFR1) and polo‐like kinase 1 (PLK1) inhibitors evoke synergistic cytotoxicity in KRAS‐mutant tumor models in vitro and in vivo." (PMID 34369083, 2021).
tumor (continued). "Because of this tumor heterogeneity, the prognostic role of KRAS mutant cancers remains uncertain, although most studies report a major aggressive behavior of this type of cancer." (PMID 35096591, 2021). "The high-IRGPI group was enriched in the KRAS signaling pathway gene set, which can affect the immune escape of tumor cells." (PMID 34722771, 2021). "Single nucleotide variations (SNV) in the Kirsten rat sarcoma viral oncogene homolog, commonly abbreviated ‘KRAS’ are present across many human tumour types with KRAS G12D and G13D being specific variants observed." (PMID 33562505, 2021). "It was reported 30–50% of CRC harbor KRAS mutations, and KRAS mutations in CRC have been associated with poorer survival and increased tumor aggressiveness." (PMID 33836681, 2021). "Low p-eIF2α results in ISR that is weakly antagonized by ISRIB52,53, thus explaining the resistance of WT KRAS tumor cells to ISRIB treatments in mice." (PMID 34330898, 2021). "KRAS-G12C inhibition has been shown to have effects on tumour-intrinsic mechanisms of immune subversion." (PMID 34200676, 2021). "PMP is a rare neoplastic disease, deriving in most cases from a mucinous appendiceal tumor from LAMN, HAMN or adenocarcinoma, all associated with co-KRAS and GNAS mutations." (PMID 34930348, 2021). "iExosomes were significantly accumulated in the G12D mutated KRAS mediated PDA cells, causing impairment of tumor cell proliferation, ameliorating apoptosis and tumbling the tumor even after treatment cessation." (PMID 34371702, 2021). "Oncogenic KRAS signalling is required for tumor initiation; however KRAS-dependency at advanced stages is less understood." (PMID 33674596, 2021). "Similar sensitivity of KRAS mutant activities to PS was also found in vivo in xenografts of human tumor lines." (PMID 34680072, 2021). "This resistance to ICI was confirmed in different tumor cell types (colorectal CT26 KRAS-mutant or EMT6 mouse mammary KRAS-WT)." (PMID 34831355, 2021). "Exosomes level and KRAS mutational status in exosomal DNA was assesed in 70 mCRC patients and 29 CRC primary tumor and were analysed at different disease steps evaluating serial blood samples (240 blood samples)." (PMID 34811396, 2021). "KRAS/STK11/KEAP1 co-mutated tumors are characterised by a lower PD-L1 expression and few tumor infiltrating lymphocytes (TILs), leading to a less immune-sensitive TME." (PMID 34944952, 2021). "An inferior survival after relapse for the panitumumab treated patients was observed, especially for the population with a mutation (either KRAS, BRAF, NRAS or PIK3CA), possibly due to accelerated tumour growth caused by the anti-EGFR therapy." (PMID 34253874, 2021). "One approach was focused on combining KRAS inhibition with epidermal growth factor receptor (EGFR) TKIs, as the EGFR signaling pathway is often activated in tumor cells to bypass KRAS inhibition." (PMID 35096591, 2021). "Mutation in KRAS, found to be present in over 90% of PDAC, is known to promote tumor carcinogenesis." (PMID 34771675, 2021). "And the GSEA results suggested that myogenesis, epithelial-mesenchymal transition (EMT), apical junction, angiogenesis, and KRAS targets were the most significant enrichment items with the progression of tumor stages." (PMID 33816287, 2021). "Out of the 33 eligible studies, 20 showed high concordance (higher than 80%) in KRAS detection results between cfDNA and tumor tissue samples." (PMID 33770081, 2021).
tumor (continued). "Mice with a mutation in a target gene, such as KrasG12D mice, which have Alb-Cre-mediated somatic KRAS activation, showed iCCA-like tumor in vivo, although tumors showed low penetrance and long latency." (PMID 34282753, 2021). "Currently, the detection of KRAS mutations is most commonly carried out in tumor tissue, especially FFPE tumor tissues." (PMID 34742312, 2021). "It is now widely accepted that KRAS extensively regulates the cross-talk between cancer and host immune cells, promoting the switch from an anti-tumor to a pro-tumor response and the development of immune escape mechanisms." (PMID 33494181, 2021). "These mutations prevent the hydrolysis of GTP to GDP, which disables the “off switch”, constitutively activating KRAS regulated signaling pathways that drive tumor growth." (PMID 33513764, 2021). "This provides a solid basis for the notion that mitochondrial metabolism is essential for KRas-mediated tumor." (PMID 35069209, 2021). "For 13 stroma-specific mutations, there were only two driver events (15.4%, KRAS G12V for P05, SMAD4 W302* for P43), while 57 driver events (42.5%) were underlined in 134 neoplasm-specific mutations." (PMID 34733795, 2021). "We identify BRAF and MYC as key mediators of KRAS-driven tumor immune suppression and show that loss of BRAF effectively blocks tumor growth in mice." (PMID 33674596, 2021). "Accordingly, cancer cells with high MGO stress showed persistent nuclear localization and activity of YAP, a key downstream target of KRAS signaling and transcriptional co-activator regulating tumor growth and invasion." (PMID 33467038, 2021). "In 55 of the patients, tumours were in advanced stages (96% stage III and IV) and with KRAS mutated (76%, 42/55) at diagnosis." (PMID 33573134, 2021). "It indicates that exosomal mutant KRAS DNA leads to this conversion, and it is further confirmed by the enrichment of FoxP3+ Tregs in tumor tissues from mutant KRAS patients, compared to the WT KRAS controls." (PMID 34616851, 2021). "The composition of the immune population and its crosstalk with KRAS altered tumor cells have a central role not only in determining tumor onset and progression but also in sensitivity to immunotherapeutic drugs." (PMID 33777798, 2021). "The median KRAS mRNA expression in tumor tissue obtained during surgery was 0.892 (range, 0.063–12.918), while the median HRAS mRNA expression was 0.978 (range, 0.054–24.194)." (PMID 33549031, 2021). "As anticipated based on existing literature, KRAS was detected in 88.3% (241/273) of tumour biopsies, with 32 samples (11.7%) being wild-type." (PMID 34956889, 2021). "The KRAS/NRAS/BRAF are the downstream effectors of the EGFR signal pathway involved in tumor cell proliferation, differentiation, and invasion." (PMID 34395262, 2021). "In this study, we found that RGS inhibited cell viability in CRC cell lines, and that this anti-tumor effect in KRAS-mutant CRC cells was significantly stronger than that in RAS wild-type cells." (PMID 34347396, 2021). "Activating mutation of KRAS is almost ubiquitous (~95%) in PDAC and is an essential event in both tumour initiation and progression." (PMID 33452856, 2021).
tumor (continued). "Wild-type KRAS or low EGFR expressing tumor cells are therefore likely to exhibit increased resistance to lysis by reovirus or cetuximab-mediated ADCC." (PMID 33933132, 2021). "This study showed that KRAS-Mφ can induce tumor cells’ resistance to cetuximab, highlighting a previously unappreciated role of KRAS in driving cetuximab resistance." (PMID 33833221, 2021). "In one case report, CRC lung metastasis patients quickly exhibited tumor regression after treatment with activated T cells recognizing G12D KRAS." (PMID 34721435, 2021). "We also assessed the association between PD-L1 membranous staining on tumor cells using 1% cut-off and the presence of the EGFR and KRAS mutations." (PMID 33956842, 2021). "An additional method by which the MAPK-ERK pathway mediates immune subversion is through the ability of KRas mutant tumor cells to generate suppressive T regulatory cells by secreting IL10 and TGFβ1." (PMID 34680208, 2021). "We uncover changes both in tumor cells and host immune cells attributable to oncogenic KRAS expression." (PMID 33674596, 2021). "Below we will discuss the main mechanisms of tumor immune resistance, with a special emphasis on LUAD and mutant KRAS-mediated effects underlying immune resistance mechanisms." (PMID 33494181, 2021). "As PTC596 and PTC208 treatments affect A549 cell cycle progression in culture, we tested their efficacy in in vivo tumor growth of human mutant-KRAS cells, by generating xenograft models of A549 cells in immunocompromised NSG mice." (PMID 33854168, 2021). "Previous studies in patients with early-stage CRC and CRLM showed worse outcomes for patients with a KRAS G12V,49-53 G12C,50-53 or G12S49 tumor mutation compared with other frequently occurring G12 variants, like G12A and G12D." (PMID 34820593, 2021). "In summary, we discovered a cell-extrinsic mechanism of KRAS involving engagement with TAMs to induce the resistance of the tumor cells to cetuximab and promote cancer progression." (PMID 33833221, 2021). "Many claudin-low tumor cells that express mutant KRAS were CD24low/CD49fhigh and lack the expression of CD61 and GATA3." (PMID 34145248, 2021). "Using imaging mass cytometry, significant changes in tumour immune contexture induced by KRAS inhibition were clearly evident." (PMID 34200676, 2021). "The LVI+ status was significantly associated with pT stage, degree of differentiation, tumor stage, serum CEA and CA19-9 levels, perineural invasion (PNI), tumor budding (TB), and KRAS status." (PMID 33866973, 2021). "Using in vitro and in vivo models, we show that oncogenic KRAS signaling within the epithelial cancer cells modulates the activity of the surrounding fibroblasts in the tumor microenvironment." (PMID 33817986, 2021). "In particular, AMG 510 potently inhibits cellular viability in KRAS G12X cell lines and induces tumor regression in xenograft models." (PMID 35004317, 2021).
tumor (continued). "For example, miR-21 can mediate ROS production by enhancing KRAS and epidermal growth factor receptor signaling, thereby promoting tumor development." (PMID 34804366, 2021). "To understand the mechanism by which KRAS engages with TAMs, we focused on the effects of KRAS on tumor cytokine profiles." (PMID 33833221, 2021). "Previous research also revealed that higher heterogeneity can be observed in KRAS mutant tumor images, and they also found some value implied the shape characteristic of the tumor, not in our research." (PMID 34026605, 2021). "The most straightforward mechanism of resistance to cetuximab is attributed to the influences of KRAS on tumor cells." (PMID 33833221, 2021). "Treatment with EMICORON, downregulated KRAS mRNA and protein expression in CRC cell lines, with decreased tumor volume in KRAS-mutated patient-derived xenografts." (PMID 34944853, 2021). "Recently, the combination of AZD0364, a selective Erk1/2 inhibitor, and selumetinib has been shown to alleviate tumor progression in multiple xenograft models of KRAS-mutant NSCLC." (PMID 34946644, 2021). "Mutational signatures, tumor mutational burden (TMB), tumor indel burden, and variants in cancer driver genes (BRAF, KRAS, POLE, POLD1 and DNA mismatch repair (MMR) genes) were analyzed for available samples." (PMID 33672345, 2021). "Arid1a inactivation is correlated to worse prognosis and poor tumor differentiation and its conditional ablation in a KRAS-driven PDAC murine model accelerated significantly invasive tumors formation, a finding underlying its tumor suppressor potential." (PMID 34771695, 2021). "The aberrant immune pathways and immune cells help to understand the tumor immune microenvironments in KRAS-mutant CRC patients." (PMID 33413474, 2021). "Previous studies have found that PP2A can inhibit the MYC gene and the AKT, KRAS, and NF-κB proteins, as well as other oncogenes and tumor signaling pathways, thereby exerting a tumor suppressor effect." (PMID 34485508, 2021). "Initially, KRAS was associated with a favorable response to ICPI, as it was more frequently associated with smokers, high tumor mutational burden (TMB) and enhanced PD-L1, as well as high infiltration of immune cells (TILs)." (PMID 35083149, 2021). "The regulatory role of miRNA on KRAS in various tumor types including CRC makes miRNAs a fascinating emerging drug therapy." (PMID 34944853, 2021). "Loss of YAP1 in epithelial cells also reduced the number of tumor promoting cancer‐associated fibroblasts and lymphocytes in early stage lesions, suggesting that YAP1 influences KRAS‐mediated tumor progression through multiple mechanisms." (PMID 34003553, 2021). "iRGD exosomes were also used to deliver KRAS siRNA specifically to αvβ3-harboring A549 tumors in vivo, resulting in specific KRAS gene knockdown and tumor growth suppression." (PMID 33537081, 2021). "Targeting the “open conformation” therefore represents a breakthrough progress for developing a new KRas-targeted anti-tumor strategy." (PMID 35069209, 2021). "In conclusion, autophagy is required for robust KRAS-driven CRC transformation by supporting tumor growth through increased glucose metabolism that specifically targets survival pathways." (PMID 33691728, 2021). "Several CDK4/6 inhibitors have been approved for metastatic breast cancer and phase I/II trials combining MEK or ERK inhibitors with the CDK4/6 inhibitor palbociclib in KRAS-mutant tumours are ongoing." (PMID 34200676, 2021).